STYK1 (STY kinase 1)
Description:
Probable tyrosine protein-kinase, which has strong transforming capabilities on a variety of cell lines. When overexpressed, it can also induce tumor cell invasion as well as metastasis in distant organs. May act by activating both MAP kinase and phosphatidylinositol 3'-kinases (PI3K) pathways (By similarity).
Synonyms: NOK; SuRTK106; DKFZp761P1010
Tractability: Small molecule: it belongs to a druggable protein family. Antibody: its Gene Ontology location is reachable by antibodies, with high confidence; UniProt predicts a signal peptide or a membrane-spanning region; the Human Protein Atlas places it where antibodies can reach. PROTAC: ubiquitination databases record sites on it.
Gene: Protein-coding gene on chromosome 12 (10,618,919 to 10,674,318, reverse strand). Ensembl gene ENSG00000060140.
Subcellular location: Membrane
Subcellular location (Human Protein Atlas): Plasma membrane; Nucleoplasm
Gene Ontology:
Molecular function: protein binding; non-membrane spanning protein tyrosine kinase activity; ATP binding; protein kinase activity; protein tyrosine kinase activity
Cellular component: plasma membrane; membrane
Genetic constraint (gnomAD): Loss-of-function variants: 46 observed, 51.68 expected, observed/expected ratio (o/e) 0.89, 90% interval 0.7 to 1.14. The upper end of that interval is the gene's LOEUF score, 1.14, which puts it in group 4 of 6, group 1 being the genes least tolerant of losing a copy. Missense variants: 527 observed, 549.43 expected, observed/expected ratio (o/e) 0.96, 90% interval 0.89 to 1.03. Synonymous variants: 188 observed, 200.09 expected, observed/expected ratio (o/e) 0.94, 90% interval 0.83 to 1.06.
Homologues: Orthologues: chimpanzee STYK1 (99% identical), macaque STYK1 (93% identical), rabbit STYK1 (83% identical), pig STYK1 (79% identical), rat Styk1 (78% identical), guinea pig STYK1 (78% identical), mouse Styk1 (78% identical), tropical clawed frog styk1 (49% identical), zebrafish styk1b (34% identical), Caenorhabditis elegans Y38H6C.20 (18% identical). Paralogues in human: FYN (25% identical), FGR (25% identical), ABL2 (25% identical), BLK (24% identical), HCK (24% identical), LCK (24% identical), YES1 (24% identical), ABL1 (24% identical), SRC (24% identical), FRK (24% identical), LYN (24% identical), CSK (23% identical), and 20 more.
Diseases named in the same sentence as STYK1 in open-access papers:
STYK1 is named in the same sentence as 29 diseases in open-access papers, as found by Europe PMC text mining. Sharing a sentence is not in itself a finding about the gene and the disease. The quoted sentences say what the papers report.
lung carcinoma (14 papers, 2015 to 2024). "Additionally, a protein called STYK1 has been identified in lung adenocarcinoma cells, which promotes lung cancer metastasis and suppresses ferroptosis through upregulating GPX4 expression." (PMID 37946181, 2023). "Preclinical discovery of STYK1 as a repressor of ferroptosis in lung cancer cells further supports that inhibition of STKY1 may be beneficial to lung cancer patients." (PMID 34742351, 2021). "In terms of mechanism, the overexpression of STYK1 in SW900 lung cancer cell line leads to upregulation of the GPX4 expression, promotes cell proliferation, and alleviates various mitochondrial abnormalities characteristic of ferroptosis, while GPX4 knocdown performed an opposite result." (PMID 34616505, 2021). "Serine threonine tyrosine kinase 1 (STYK1, also known as NOK), a member of the receptor tyrosine kinases (RTKs) family, can promote metastasis of lung cancer through inducing epithelial-mesenchymal transition (EMT) by activating the AKT/glycogen synthase kinase 3 beta (GSK3B) pathway." (PMID 34742351, 2021). "Therefore, we can conclude that STYK1/NOK regulates ferroptosis in lung cancer cells negatively." (PMID 34616505, 2021). "High levels of STYK1/NOK expression have been reported in many types of cancers including leukemia, lung cancer, breast cancer and colorectal cancer etc." (PMID 36506394, 2022). "STYK1 shows carcinogenicity by increasing the expression of GPX4 and then controlling ferroptosis in lung cancer cells." (PMID 35875069, 2022). "This highlights the potential selectivity of the combined targeting of STYK1 and EGFR for EGFR-mutant lung cancer cells." (PMID 35840561, 2022). "High expression of serine-threonine tyrosine kinase 1 (STYK1) in NSCLC cell line SW900 promotes the expression of GPX4 and the proliferation of lung cancer cells." (PMID 34630843, 2021). "Subsequent mechanistic studies have shown that overexpression of STYK1 up-regulates expression of GPX4 protein, resulting in decreased sensitivity of lung cancer SW900 cells to ferroptosis." (PMID 34742351, 2021). "Targets such as Nrf2, LSH, STYK1/NOK, and ACSL4 also hold significant promise in the field of ferroptosis in lung cancer." (PMID 39944353, 2024). "Of these genes, human homologs of 4 genes including Inhibin, beta A (INHBA), Kruppel-like factor 5 (KLF5), Serine/threonine/tyrosine kinase 1 (STYK1), and stem cell marker ALDH1A1 are previously shown to be over-expressed in NSCLC and involved in lung cancer progression and tumorigenicity." (PMID 28415606, 2017). "However, a lot of studies have reported that the inhibition of ferroptosis is ubiquitous in lung cancer cells; for example, xCT (SLC7A11), serine/threonine/tyrosine kinase 1 (STYK1), and iron–sulfur cluster biosynthetic enzyme (NFS-1) have been found to be highly expressed in NSCLC cells." (PMID 35875069, 2022).
non-small cell lung carcinoma (9 papers, 2014 to 2024). A group of at least three distinct histological types of lung cancer, including non-small cell squamous cell carcinoma, adenocarcinoma, and large cell carcinoma. "STYK1 over-expression has been related to many types of tumors, such as prostate cancer cells leukemia cells, breast cancer, non-small cell lung cancer, ovarian cancer, and colorectal cancer." (PMID 29340057, 2017). "Moreover, non-small cell lung cancer A549 cells that stably overexpressing STYK1 shRNA were generated and the phosphorylation levels of EGFR downstream effector were tested." (PMID 37192859, 2022). "Non-small cell lung cancer cell lines with the overexpression or knockdown of STYK1 were established to determine whether STYK1 promotes cell migration, invasion, and EMT in vitro and in vivo." (PMID 34295886, 2021). "In addition, the prognostic value of STYK1 protein expression in non-small cell lung cancer has also been revealed." (PMID 25884558, 2015).
pancreatic cancer (4 papers, 2017 to 2025). "Taken together, these results indicated that loss of STYK1 inhibits pancreatic cancer proliferation and delays PDAC progression." (PMID 40588478, 2025). "Although it is contradictory that mTOR plays negative roles in autophagy, it shows the collaborate of mTOR and autophagy mediated by STYK1 at least in the cases of EGFR-TKIs resistance or pancreatic cancer with activating KRAS mutations and high basal autophagy." (PMID 37192859, 2022). "To gain insights into the molecular mechanisms underlying the role of STYK1 in pancreatic cancer tumorigenicity, we performed global gene expression analysis of pancreatic cancer cells that were stably transfected with STYK1 shRNA by RNA sequencing (RNA-Seq)." (PMID 40588478, 2025). "This prompted a focused investigation into STYK1’s functional implications within pancreatic cancer." (PMID 40588478, 2025). "Given the roles of STYK1 in the activation of Wnt/β-catenin pathway and pancreatic cancer progression, we evaluated STYK1-driving peptides disrupting STYK1-β-catenin/GSK3β interactions on pancreatic cancer tumorigenesis." (PMID 40588478, 2025). "Interrogation of the GEPIA2 transcriptomic database revealed that STYK1 is overexpressed in several types of human cancers, especially pancreatic cancer." (PMID 40588478, 2025). "Immunohistochemical (IHC) profiling of pancreatic cancer tissue microarrays revealed stage-dependent STYK1 overexpression, showing marked elevation in pancreatic cancer cells." (PMID 40588478, 2025). "Collectively, these results elucidate a novel STYK1-driven mechanism for Wnt/β-catenin activation in APC-independent pancreatic cancer and provide preclinical evidence for targeting STYK1-mediated signaling as a therapeutic strategy." (PMID 40588478, 2025). "Collectively, these data indicate that STYK1-driving peptides show efficient effects in inhibiting pancreatic cancer development." (PMID 40588478, 2025). "Collectively, our findings establish STYK1 as a modulator of Wnt/β-catenin signaling and confirm its therapeutic targeting potential in pancreatic cancer." (PMID 40588478, 2025). "By using multiple in vitro and in vivo assays, we figured out that higher STYK1 expression is related to poor pancreatic cancer survival and that STYK1 depletion suppresses pancreatic cancer cell development." (PMID 40588478, 2025). "We next constructed tumor xenograft models by subcutaneously injecting PANC-1 cells to investigate the role of STYK1 in pancreatic cancer in vivo." (PMID 40588478, 2025). "STYK1 and E-cadherin mRNA expression were detected by semi-quantitative RT-PCR in 20 cases of pancreatic cancer tissue samples and paired adjacent normal tissue samples." (PMID 29340057, 2017). "E-cadherin expression was inversely correlated with STYK1 expression in pancreatic cancer tissue samples." (PMID 29340057, 2017). "Our results indicated that STYK1 promoted pancreatic cancer progression, possibly through p38 MAPK-mediated EMT procession." (PMID 29340057, 2017). "Here, we investigated the prognostic significance of aberrant STYK1 and E-cadherin in pancreatic cancer." (PMID 29340057, 2017). "STYK1 repressed E-cadherin expression and promoted EMT, mediated by p38 MAPK signaling pathway, which was the possible mechanism for STYK1-mediated pancreatic cancer cell proliferation and migration." (PMID 29340057, 2017).
pancreatic cancer (continued). "We found that mRNA and protein expression of STYK1 were higher while mRNA and protein expression of E-cadherin was lower in pancreatic cancer cell lines compared with HPDE cells." (PMID 29340057, 2017). "Our results showed that STYK1 expression increased while E-cadherin decreased in pancreatic cancer tissues compared with normal pancreas tissues." (PMID 29340057, 2017). "Immunohistochemical analysis of 80 paired pancreatic cancer specimens revealed that STYK1 was mainly localized in the cytoplasm, and 87.5% (70/80) of the tumor tissues tested were positive staining." (PMID 29340057, 2017). "Taken together, the present study indicated that STYK1 promotes pancreatic cancer cell proliferation and migration through enhancing EMT that mediated by p38 MAPK signaling pathway." (PMID 29340057, 2017). "In this study, we focused on STYK1 and E-cadherin expression and their correlations in pancreatic cancers patients and its possible mechanisms." (PMID 29340057, 2017). "STYK1 level was positively correlated with lymph node metastasis and clinical stage in pancreatic cancer patients." (PMID 29340057, 2017). "In this study, we explored the expression of STYK1 and E-cadherin in pancreatic cancer, and analyzed the relationship between their expression levels and clinico-pathological features in the patients with pancreatic cancer." (PMID 29340057, 2017). "We next analyzed the relationship between E-cadherin and STYK1 expression with clinico-pathological features in patients of pancreatic cancer." (PMID 29340057, 2017). "Compared with normal tissue samples, STYK1 was highly upregulated in most of pancreatic cancer tissue samples, whereas E-cadherin mRNA levels were significantly lower in most of tumor samples." (PMID 29340057, 2017). "In conclusion, the present study demonstrated that STYK1 was highly expressed pancreatic tumor tissues and was significantly correlated with the prognosis of pancreatic cancer." (PMID 29340057, 2017). "Next, we analyzed correlations between STYK1 and E-cadherin in pancreatic cancers with different clinical stage." (PMID 29340057, 2017). "Notably, inhibitory peptides targeting either the STYK1-β-catenin or the STYK1-GSK3β interface significantly suppressed pancreatic cancer development in vitro and in vivo, underscoring their therapeutic potential." (PMID 40588478, 2025). "Additionally, the effects of STYK1-derived peptides that target its interaction with GSK3β and β-catenin were also investigated in pancreatic cancer mice models." (PMID 40588478, 2025). "Cell apoptosis was revealed by Annexin V/PI staining in AsPC1 and PANC1 cells and the results maintained that STYK1 knockdown could increase the apoptosis of pancreatic cancer cells." (PMID 29340057, 2017). "In addition, STYK1 knockdown in pancreatic cancer cell lines inhibited cell proliferation, enhanced cell apoptosis, induced cell cycle arrest, and prohibited cell migration, while STYK1 over-expression showed the opposite effects." (PMID 29340057, 2017). "In addition, we verified the oncogenic role of STYK1 by using pancreatic cancer cell lines through regulating p38 MAPK-mediated EMT in vitro." (PMID 29340057, 2017). "We have found that STYK1 was upregulated in pancreatic cancer, and then we would like to explore whether it could alter the biological phenotype of pancreatic cancer." (PMID 29340057, 2017). "In summary, our results showed that STYK1 might be a prognostic marker for pancreatic cancer patients and might be a novel strategy for the treatment of pancreatic cancer." (PMID 29340057, 2017). "To further investigate the association of survival time with E-cadherin and STYK1 expression, a final concomitant model was constructed and we found that a combinatorial pattern of high E-cadherin expression and low STYK1 predicted the better clinical prognosis in pancreatic cancer." (PMID 29340057, 2017). "We then went further to explore whether STYK1 could change the phenotype of pancreatic cancers." (PMID 29340057, 2017).
pancreatic cancer (continued). "Expectedly, the endogenous interaction between GSK3β, β-catenin, and STYK1 was confirmed using immunoprecipitation and immunofluorescence assays with specific antibodies in AsPC-1, PANC-1, SW1990, and MIA-PACA-2 cells and pancreatic cancer patient's tissues." (PMID 40588478, 2025). "Our research was to analyze the clinical significance of STYK1 and showed that over-expression of STYK1 protein was significantly correlated with clinical stage and lymph node metastasis, indicating that STYK1 might be involved in the progression of pancreatic cancer." (PMID 29340057, 2017). "Finally, we tested the relationship between STYK1 and E-cadherin in human normal pancreatic epithelial cell line HPDE and in pancreatic cancer cell lines in vitro." (PMID 29340057, 2017). "Thus, STYK1 repressed E-cadherin expression and promoted EMT, mediated by p38 MAPK signaling pathway, which was the possible mechanism for STYK1-mediated pancreatic cancer cell proliferation and migration." (PMID 29340057, 2017). "We examined STYK1 and E-cadherin mRNA and protein expression in pancreatic cancer tissues and corresponding adjacent non-cancerous tissues, and we found that strong STYK1 and weak E-cadherin expression in tumor tissues samples compared with normal tissue samples." (PMID 29340057, 2017). "However, there was no clinical investigation of STYK1 on pancreatic cancer." (PMID 29340057, 2017).
colorectal cancer (3 papers, 2015 to 2025). A primary or metastatic malignant neoplasm that affects the colon or rectum. "Aberrant expression of serine threonine tyrosine kinase 1 (STYK1) has been reported in several human malignancies including colorectal cancer (CRC)." (PMID 25884558, 2015). "It has been showed that STYK1 mRNA might be a tool to support the diagnosis of breast, lung, and colorectal carcinomas." (PMID 25884558, 2015).
hepatocellular carcinoma (3 papers, 2016 to 2024). A malignant tumor that arises from hepatocytes. "We found that silencing STYK1 increases E-cadherin expression, whereas decreased mesenchymal markers, which was consistent with previous research in hepatocellular carcinoma." (PMID 29340057, 2017).
prostate carcinoma (3 papers, 2016 to 2022). A carcinoma that arises from epithelial cells of the prostate gland. "This tendency is consistent with STYK1 overexpression in many other malignancies, except for gastric cancer and some cases of castration-naïve prostate cancer." (PMID 34295886, 2021). "Experiments with a kinase-dead version of STYK1 have confirmed that STYK1 residual kinase activity is required to promote the growth of prostate cancer cells in vitro, although no direct substrates of STYK1 have been reported until now." (PMID 35840561, 2022).
acute leukemia (2 papers, 2015 to 2024). A clonal (malignant) hematopoietic disorder with an acute onset, affecting the bone marrow and the peripheral blood. "Moreover, it has been clarified recently that measurement of STYK1 mRNA expression could be a potential marker for predicting the therapeutic outcome of various types of acute leukemia." (PMID 25884558, 2015).